DHX35 (DEAH-box helicase 35)
Description:
Acts as a co-sensor in RIGI-mediated antiviral innate immunity. Enhances RIGI recognition of viral nucleic acids and interacts with RIGI and MAVS to form a signaling complex which triggers downstream signaling cascades that lead to the induction of type I interferons and pro-inflammatory cytokines during the antiviral innate immune response.
Synonyms: C20orf15; DDX35; FLJ22759; KAIA0875
Tractability: PROTAC: ubiquitination databases record sites on it; its protein half-life has been measured.
Target class: Enzyme; Hydrolase
Gene: Protein-coding gene on chromosome 20 (38,962,299 to 39,039,723, forward strand). Ensembl gene ENSG00000101452.
Subcellular location: Nucleus; Cytoplasm
Subcellular location (Human Protein Atlas): Nuclear bodies; Centrosome; Nucleoplasm
Pathways (Reactome):
Metabolism of RNA: mRNA Splicing - Major Pathway
Gene Ontology:
Molecular function: double-stranded DNA binding; double-stranded RNA binding; protein binding; helicase activity; ATP hydrolysis activity; RNA helicase activity
Biological process: antiviral innate immune response; positive regulation of interferon-beta production; positive regulation of interleukin-6 production; positive regulation of IP-10 production; positive regulation of RIG-I signaling pathway; mRNA splicing, via spliceosome
Cellular component: catalytic step 2 spliceosome; cytoplasm; nucleus; nucleoplasm
Genetic constraint (gnomAD): Loss-of-function variants: 75 observed, 90.18 expected, observed/expected ratio (o/e) 0.83, 90% interval 0.69 to 1.01. The upper end of that interval is the gene's LOEUF score, 1.01, which puts it in group 4 of 6, group 1 being the genes least tolerant of losing a copy. Missense variants: 790 observed, 859.96 expected, observed/expected ratio (o/e) 0.92, 90% interval 0.87 to 0.97. Synonymous variants: 312 observed, 312.71 expected, observed/expected ratio (o/e) 1, 90% interval 0.91 to 1.1.
Homologues: Orthologues: chimpanzee DHX35 (99% identical), macaque DHX35 (99% identical), pig DHX35 (97% identical), guinea pig DHX35 (96% identical), dog DHX35 (96% identical), mouse Dhx35 (95% identical), rat Dhx35 (95% identical), rabbit DHX35 (95% identical), tropical clawed frog dhx35 (84% identical), zebrafish dhx35 (54% identical), Caenorhabditis elegans ddx-35 (53% identical), Drosophila melanogaster CG3225 (47% identical), and 1 more. Paralogues in human: DHX8 (46% identical), DHX16 (44% identical), DHX15 (43% identical), DHX38 (42% identical), DHX33 (41% identical), DHX37 (37% identical), DHX40 (32% identical), DHX57 (32% identical), DHX34 (31% identical), DQX1 (31% identical), DHX32 (30% identical), DHX29 (30% identical), and 6 more.
Diseases named in the same sentence as DHX35 in open-access papers:
DHX35 is named in the same sentence as 10 diseases in open-access papers, as found by Europe PMC text mining. Sharing a sentence is not in itself a finding about the gene and the disease. The quoted sentences say what the papers report.
breast carcinoma (2 papers, 2015 to 2024). "DHX35 is highly expressed in human hepatocellular carcinoma and breast cancer cells and promotes carcinogenesis." (PMID 39037956, 2024). "The DHX35 gene has previously been identified as a 5′ fusion partner to the ITCH gene in the SK-BR-3 breast cancer cell line, indicating that it may be a 5′ partner in multiple fusion genes." (PMID 26474385, 2015).
hepatocellular carcinoma (1 paper, 2024). A malignant tumor that arises from hepatocytes. "It has been reported that high DHX35 expression predicts poor prognosis in patients with hepatocellular carcinoma." (PMID 39037956, 2024).
scoliosis (1 paper, 2021). A congenital or acquired spinal deformity characterized by lateral curvature of the spine. "The mutant of its family member DHX35 was described to have abnormal vertebrae morphology and scoliosis in mice (MGI: 1918965)." (PMID 34440387, 2021).
viral infections (1 paper, 2024). "Our results demonstrate a novel molecular mechanism for DHX35 in RIG-I-mediated innate immunity and provide a novel candidate for drug and vaccine design to control viral infections in the human airway." (PMID 39037956, 2024).
cancer (2 papers, 2017 to 2024). A tumor composed of atypical neoplastic, often pleomorphic cells that invade other tissues. "A previous study reported that DHX35 knockdown suppressed replication of myxoma virus, a member of the dsDNA poxvirus family, in human cancer cells, including A549 cells." (PMID 39037956, 2024). "A study reported that DHX35 knockdown suppressed myxoma virus (a dsDNA virus) replication in human cancer cells; however, its expression and location are unknown in human airway epithelial cells." (PMID 39037956, 2024). "Furthermore, DHX35 knockdown suppresses the replication of myxoma virus, a double-stranded DNA (dsDNA) virus, in human cancer cells." (PMID 39037956, 2024).
tumor (2 papers, 2020 to 2025). "We also detected the age-related effect of rs1867277 (FOXE1) conferring the higher risk for PTC in patients older than 55 years and the association of rs7267944 (DHX35) with PTC risk in males and that of rs6983267 (POU5F1B/CCAT2) with more advanced tumor pT stage." (PMID 33551988, 2020). "Similarly, the RNA modification-related genes DHX35, DHX8, ENY2, and FTSJ1 also upregulated in most tumor tissues." (PMID 40041484, 2025).
infection (1 paper, 2024). The state of being infected such as from the introduction of a foreign agent such as serum, vaccine, antigenic substance or organism. "Taken together, these results indicate that DHX35 is constitutively expressed and translocated into the cytosol, where it interacts with cytosolic nucleic acids upon infection in human airway epithelial cells." (PMID 39037956, 2024).
DHX35 also shares sentences with these, for which no sentence is quoted: thyroid cancer (2 papers); autism (1); cardiovascular diseases (1).